SMARCA2 (SWI/SNF related BAF chromatin remodeling complex subunit ATPase 2)
Description:
ATPase involved in transcriptional activation and repression of select genes by chromatin remodeling (alteration of DNA-nucleosome topology). Component of SWI/SNF chromatin remodeling complexes that carry out key enzymatic activities, changing chromatin structure by altering DNA-histone contacts within a nucleosome in an ATP-dependent manner. Binds DNA non-specifically. Belongs to the neural progenitors-specific chromatin remodeling complex (npBAF complex) and the neuron-specific chromatin remodeling complex (nBAF complex). During neural development a switch from a stem/progenitor to a postmitotic chromatin remodeling mechanism occurs as neurons exit the cell cycle and become committed to their adult state. The transition from proliferating neural stem/progenitor cells to postmitotic neurons requires a switch in subunit composition of the npBAF and nBAF complexes. As neural progenitors exit mitosis and differentiate into neurons, npBAF complexes which contain ACTL6A/BAF53A and PHF10/BAF45A, are exchanged for homologous alternative ACTL6B/BAF53B and DPF1/BAF45B or DPF3/BAF45C subunits in neuron-specific complexes (nBAF). The npBAF complex is essential for the self-renewal/proliferative capacity of the multipotent neural stem cells. The nBAF complex along with CREST plays a role regulating the activity of genes essential for dendrite growth (By similarity).
Synonyms: SAMRCA2; hBRM; BRM; SNF2L2; BAF190; hSNF2a; Sth1p; SNF2LA; SNF2; SWI2; BIS; NCBRS
Tractability: Small molecule: a structure with a bound ligand is known; a high-quality ligand is known. PROTAC: it is named in the literature on targeted protein degradation; UniProt records ubiquitination sites on it; ubiquitination databases record sites on it; its protein half-life has been measured; a small molecule that binds it is known.
Target class: Epigenetic regulator; Bromodomain; Reader
Chemical probes: ACBI1 (high quality), ACBI2 (high quality), FHT-2344 (high quality), GNE-064 (high quality), PFI-3 (high quality), SGC-SMARCA-BRDVIII (high quality)
Gene: Protein-coding gene on chromosome 9 (1,980,290 to 2,193,624, forward strand). Ensembl gene ENSG00000080503.
Subcellular location: Nucleus
Subcellular location (Human Protein Atlas): Nucleoplasm; Plasma membrane; Vesicles
Pathways (Reactome):
Chromatin organization: Formation of neuronal progenitor and neuronal BAF (npBAF and nBAF); Formation of the canonical BAF (cBAF) complex; Formation of the non-canonical BAF (ncBAF) complex; Formation of the polybromo-BAF (pBAF) complex; RMTs methylate histone arginines
Gene expression (Transcription): RUNX1 interacts with co-factors whose precise effect on RUNX1 targets is not known; Regulation of endogenous retroelements by Piwi-interacting RNAs (piRNAs)
Developmental Biology: Regulation of MITF-M-dependent genes involved in pigmentation
Gene Ontology:
Molecular function: ATP hydrolysis activity; protein binding; transcription cis-regulatory region binding; transcription coactivator activity; ATP-dependent activity, acting on DNA; helicase activity; ATP binding; chromatin binding; histone binding
Biological process: negative regulation of cell growth; negative regulation of cell population proliferation; negative regulation of DNA-templated transcription; positive regulation of DNA-templated transcription; positive regulation of transcription by RNA polymerase II; chromatin remodeling; negative regulation of cell differentiation; negative regulation of transcription by RNA polymerase II; positive regulation of cell differentiation; positive regulation of cell population proliferation; positive regulation of double-strand break repair; positive regulation of myoblast differentiation; positive regulation of stem cell population maintenance; positive regulation of T cell differentiation; regulation of DNA-templated transcription; regulation of G0 to G1 transition; regulation of G1/S transition of mitotic cell cycle; regulation of mitotic metaphase/anaphase transition; regulation of nucleotide-excision repair; regulation of transcription by RNA polymerase II; spermatid development
Cellular component: chromatin; nucleoplasm; nucleus; SWI/SNF complex; bBAF complex; brahma complex; GBAF complex; nBAF complex; npBAF complex
Genetic constraint (gnomAD): Loss-of-function variants: 34 observed, 142.86 expected, observed/expected ratio (o/e) 0.24, 90% interval 0.18 to 0.32. The synonymous counts are far from expectation, so gnomAD's model fits this gene poorly and the ratio says little. Missense variants: 1,128 observed, 1,647.8 expected, observed/expected ratio (o/e) 0.68, 90% interval 0.65 to 0.72. Synonymous variants: 773 observed, 615.56 expected, observed/expected ratio (o/e) 1.26, 90% interval 1.18 to 1.33.
Gene-disease validity (ClinGen):
ClinGen rates the evidence that SMARCA2 causes each of these diseases.
intellectual disability-sparse hair-brachydactyly syndrome (autosomal dominant): Definitive. Intellectual disability-sparse hair-brachydactyly syndrome is a very rare condition of unknown etiology consisting of short stature, hypotrichosis, brachydactyly with cone-shaped epiphyses, epilepsy and severe mental delay.
Homologues: Orthologues: macaque SMARCA2 (99% identical), dog SMARCA2 (98% identical), chimpanzee SMARCA2 (97% identical), rabbit SMARCA2 (97% identical), mouse Smarca2 (97% identical), rat Smarca2 (97% identical), guinea pig SMARCA2 (97% identical), tropical clawed frog smarca2 (86% identical), Drosophila melanogaster brm (55% identical), zebrafish si:dkey-226m8.10 (9% identical). Paralogues in human: SMARCA4 (78% identical), CHD7 (23% identical), EP400 (22% identical), CHD2 (22% identical), SRCAP (22% identical), CHD1 (22% identical), CHD5 (21% identical), CHD9 (21% identical), CHD3 (21% identical), CHD8 (20% identical), CHD4 (20% identical), CHD6 (20% identical), and 18 more.
Diseases named in the same sentence as SMARCA2 in open-access papers:
SMARCA2 is named in the same sentence as 158 diseases in open-access papers, as found by Europe PMC text mining. Sharing a sentence is not in itself a finding about the gene and the disease. The quoted sentences say what the papers report.
lung cancer (45 papers, 2013 to 2025). A malignant neoplasm involving the lung. "Several studies involving clinical cases, cell lines, and animal models of lung cancer indicate a worse prognosis associated with SMARCA2 and SMARCA4 deficiency in the disease." (PMID 39888726, 2025). "Among tumors with SWI/SNF chromatin remodeling abnormalities, loss of SMARCA4 and SMARCA2 protein expression has been shown to be a poor prognostic factor, particularly in lung cancer." (PMID 40866717, 2025). "Since then, several studies involving primary tumors, cell lines, and animal models of lung cancer have shed more light on the role of SMARCA2 and SMARCA4 deficiency in the disease." (PMID 39888726, 2025). "SMARCA4 deficiency is observed in about 5% of conventional non‐small cell lung cancers, which should be distinguished by epithelial architecture, diffuse strong keratin expression and ancillary marker including SMARCA2." (PMID 35822082, 2022). "On one hand, frequent loss of SMARCA2 expression was observed in patients with lung cancer and gastric cancer." (PMID 34315468, 2021). "A sensitivity to SMARCA2 loss by RNA interference knockdown was observed in SMARCA4-deficient lung cancers, which triggered a phenotypic lethal response." (PMID 33941852, 2021). "SMARCA2 has been identified as an essential gene in lung cancer cells that harbor SMARCA4 mutations." (PMID 34298819, 2021). "Inactivating mutations in SMARCA4 and concurrent epigenetic silencing of SMARCA2 characterize subsets of ovarian and lung cancers." (PMID 34518526, 2021). "For example, decreased SMARCA2 expression has been documented in several cancer cell lines and primary cancers, and was significantly associated with poor survival of lung cancer patients." (PMID 34298819, 2021). "The existence of homozygous insertional polymorphisms of the SMARCA2 promoter, located −741 bp and −1321 bp from the transcription start site, has previously been linked to loss of SMARCA2 expression in lung cancer." (PMID 32575483, 2020). "Thus, CBP/p300 dual inhibitors could be promising for SMARCA4/SMARCA2-deficient lung cancer and SS18–SSX fusion synovial sarcoma, which are entirely deficient in the cBAF complex." (PMID 39625239, 2025). "Multi-omics analysis and in vitro experiments identified SMARCA2 as a tumor suppressor gene with decreased expression in lung cancer, showing that its inactivation can be epigenetically driven by promoter hypermethylation." (PMID 39888726, 2025). "Here, we describe a rare case of small cell lung cancer (SCLC) with SMARCA4 loss, characterized by an aggressive phenotype, and further discuss the molecular, pathological, and clinical features of SMARCA2 and SMARCA4 deficiency in lung cancer." (PMID 39888726, 2025). "Inactivation of SMARCA2 and SMARCA4 in a mouse model resulted in accelerated lung tumor development and loss of differentiation, closely resembling human lung cancer characterized by local tumor invasion and distant metastasis." (PMID 39888726, 2025). "Here we show that ACBI2 is capable of inducing near-complete degradation of SMARCA2 in mouse lung cancer xenograft models that leads to tumour growth inhibition." (PMID 36216795, 2022). "The SMARCA2 gene also demonstrates context-dependent vulnerabilities in several tissue types including lung cancers." (PMID 34298819, 2021). "The potential of SMARCA4 and its mutually exclusive paralog SMARCA2 as therapeutic target has been already investigated in the case of lung cancer using an allosteric SMARCA4/SMARCA2 inhibitor." (PMID 33572108, 2021). "Hence, selective degradation of the SWI/SNF ATPase SMARCA2 by PROTACs YDR1 or YD54 was found to provide better sensitivity in SMARCA4 mutant xenografted lung cancer cells." (PMID 41278204, 2025).
lung cancer (continued). "SMARCA4-mutant lung cancer cells with intact SMARCA2 depend on elevated OXPHOS activity by upregulating the master transcription factor PGC-1a38, whereas ARID1A inactivation in ovarian cancer cells causes reliance on glutamine metabolism through activating glutaminase expression." (PMID 37210563, 2023). "SMARCA2 is a tumor suppressor gene, and hypermethylation can drive lung cancer development." (PMID 37356052, 2023). "SMARCA2 and SMARCA4 deficiency was noted in 10% of nonsmall cell lung cancer cases, 80% of SMARCA2/SMARCA4 deficient tumors was also TTF-1 negative, and recently SMARCA4 loss was found to be a predictor of response to platinum based chemotherapy." (PMID 31093468, 2018). "In addition, ovarian and lung cancers deficient in one SWI/SNF subunit appear sensitive to loss (by RNAi depletion) of the alternative subunit, e.g. SMARCA2 depletion in SMARCA4-deficient lung cancer cells." (PMID 29515757, 2018). "Non–small cell lung cancer harboring a SMARCA4/SMARCA2 deficiency has no established treatment because it is mutually exclusive to genetic abnormalities such as EGFR mutations and anaplastic lymphoma kinase (ALK) and RET fusions, for which there are established treatments." (PMID 39625239, 2025). "This resulted in compound 6, a fast and potent dual degrader of SMARCA2/4 (SMARCA2 DC50 = 2 nM, Dmax = 77%; SMARCA4 DC50 = 5 nM, Dmax = 86%, in RKO cells after 4 h) that displayed the expected anti-proliferative effect (EC50 = 2 nM) in a SMARCA4-deficient lung cancer cell line, NCI-H1568." (PMID 36216795, 2022). "This hypothesis is also supported by recent evidence showing that PFI-3, a selective SMARCA4/2 BRDi, fails to phenocopy the observed SMARCA2-depleted phenotype in SMARCA4-deficient lung cancer cells." (PMID 31000698, 2019). "For example, an orally available allosteric inhibitor of both SMARCA2 and SMARCA4 has been discovered and has demonstrated antiproliferative activity in a mouse xenograft model of SMARCA4-mutant lung cancer." (PMID 36418306, 2022). "An allosteric inhibitor of SMARCA2 and SMARCA4 has demonstrated anti-proliferative activity in a mouse xenograft model of SMARCA4-mutant lung cancer." (PMID 34359794, 2021). "However, lung carcinomas, such as NSCLC, primary adenocarcinomas, and squamous cell carcinomas, are represented by a combination of an epigenetic silencing mutation of the SMARCA4 gene and SMARCA2 gene, which are primarily located at the chromosome 9p24.3, which encodes the BRM protein." (PMID 34440689, 2021). "Furthermore, in rhabdomyosarcoma, evidence indicates a protein-protein interaction between members of mSWI/SNF (SMARCA2) and GLI-1, consistent with our findings in lung cancer, where SMARCB1 interacts with GLI-1." (PMID 39971779, 2025). "Furthermore, HDACi, a class of anti-cancer drugs that blocks the deacetylation of chromatin and other cellular substrates involved in cancer initiation and progression, has also been shown to reactivate SMARCA2 expression in SCCOHT and lung cancer cells." (PMID 34518526, 2021). "This has significant implications for small-molecule drug discovery as SMARCA2 knock-down causes cancer-specific, phenotypic lethality in SMARAC4-null lung cancers, but bromodomain inhibition does not phenocopy the effects of RNAi-mediated target depletion." (PMID 26396593, 2015). "Extending on our above findings, in DepMap RNA-seq datasets of ovarian and lung cancer cell line panels, the expression of SLC2A1 mRNA significantly and positively correlated with that of SMARCA2 and SMARCA4 in cells with low (bottom quartile) SMARCA4 or SMARCA2 expression, respectively." (PMID 37210563, 2023).
breast carcinoma (26 papers, 2009 to 2025). "We also identified three known poly-glutamine repeat polymorphisms, one in exon 20 of NCOA3., one in exon 15 of NCOR2., and one in exon 4 of SMARCA2; associations with these repeat polymorphisms and breast cancer risk will be examined in future studies." (PMID 19183483, 2009). "In breast cancer cell lines in vitro, the overexpression of SMARCA2 was suppressed, whereas SMARCA2 knockdown promoted TGF-β-induced migration and invasion of cancer cells." (PMID 36674511, 2023). "Analysis of rare missense variants identified evidence of associations of TMEM161A, SIPA1L1, and ERCC2 with overall breast cancer, RNF175 and NCKAP1L with ER-positive disease, and SLC22A10, PHAX, SMARCA2, EML5, NTRK3, and MED23 with ER-negative disease." (PMID 35884425, 2022). "When missense variants were assessed, three further associations were observed for overall breast cancer (TMEM161A, SIPA1L1, ERCC2), and a further seven were observed for subtypes (RNF175, NCKAP1L, PHAX, SMARCA2, EML5, NTRK3, MED23)." (PMID 35884425, 2022). "The specificity of used antibody against BAF155 and BRM was validated on breast cancer cell line with amiRNA targeting SMARCC1 or SMARCA2." (PMID 32073734, 2020). "By contrast, a statistically significant downregulation of SMARCA2 transcript was observed in all breast cancer types comparing to healthy tissue." (PMID 31722744, 2019). "Based on this observation, it was postulated that expression of SMARCA2 and SMARCA4 has prognostic value, although another study shows that the BRM protein level varies among various breast cancer types." (PMID 31722744, 2019). "Additionally, we identified the alterations of epigenetic targets, such as SWI/SNF related genes (SMARCA2, SMARCA4, SMARCA5) or histone modifiers (KMT2C or KMT2D), breast cancer-associated oncogenes (MYCN or MAPKs), or genes that are involved in drug-resistance (ESR1 and PIK3CA/B)." (PMID 31216647, 2019). "In breast cancer tissues, SMARCA2 (or BRM) and SMARCA4 (Brahma-related Gene 1, BRG1) ATPases were overexpressed, in most cases independently of the hormone receptor status." (PMID 35761157, 2022). "The best putative candidates in this group were TMEM161A, ERCC2, and SIPA1L1 for overall breast cancer, RNF175 and NCKAP1L for ER-positive disease, and PHAX, SMARCA2, NTRK3, EML5, and MED23 for ER-negative disease." (PMID 35884425, 2022). "Some specific targets and pathways were mainly enriched in the c2.all.v6.2.entrez.gmt gene set, suggesting that progression of MPM may partly be involved in the invasive pathways of breast cancer and pathways related to TCF21 and SMARCA2 targets." (PMID 33968720, 2021).
melanoma (16 papers, 2013 to 2025). A malignant, usually aggressive tumor composed of atypical, neoplastic melanocytes. "SMARCA4 and its paralogue SMARCA2 are almost equally frequently mutated (mostly as missenses) in patients with melanoma." (PMID 36844227, 2023). "In light of accumulated data, ARID2, ARID1B, SMARCA4 (BRG1), and SMARCA2 (BRM) have the most important mutations in melanoma." (PMID 36844227, 2023). "SMARCA2 mutations occur at almost the same frequency as SMARCA4 mutations in patient derived melanomas." (PMID 35323214, 2022). "Depletion of SMARCA2 in SMARCA4-deficient melanoma cells abrogates melanoma tumorigenicity and systematic studies in other cancers have shown that loss of one subunit renders cells highly dependent on the paralogous subunit." (PMID 35323214, 2022). "It will be important to further evaluate potential synthetic lethality between SMARCA4 and SMARCA2 in melanoma." (PMID 35323214, 2022). "Melanoma ranks as the fourth most common cancer with SMARCA2 genetic alterations." (PMID 35323214, 2022). "Despite this hypothesis, SMARCA2 was shown to interact with MITF and to partially compensate for SMARCA4 loss in the regulation of MITF-target genes in melanoma cells." (PMID 35323214, 2022). "SMARCA2, a member of the SWI/SNF family, is involved in melanocyte differentiation and melanoma." (PMID 34220935, 2021). "Interestingly, SMARCA2 and ARID1B alterations were mainly homozygous deletions, possibly because they map to chromosomes 9p and 6q, respectively, which are commonly affected by arm-level losses in melanoma, whereas alterations of other genes constituted indels and SNVs." (PMID 35706047, 2022).